IGF1R (insulin like growth factor 1 receptor)
Diseases named in the same sentence as IGF1R in open-access papers (continued):
Sharing a sentence is not in itself a finding about the gene and the disease.
prostate carcinoma (continued). "BMMSCs could attenuate the progression of prostate cancer, and exosomal miR-99b-5p and IGF1R were involved in the regulatory process." (PMID 38994350, 2024). "Higher-grade tumors (primary GS = 4–5) contain significantly more IGF-1R than lower-grade tumors (primary GS = 3) (p = 0.004);The risk of overall recurrence was significantly greater in men whose prostate cancers contained high total- and cytoplasmic- IGF-1R (p = 0.002)." (PMID 36831629, 2023). "IGF1R is currently being investigated as a potential biomarker in metastatic prostate cancers, as appropriate biomarkers that may be derived in the blastic bone phenotype have not yet been identified." (PMID 36054271, 2023). "Moreover, NRP2, in concert with VEGF, regulates IGF-1R expression and signaling in prostate cancer cells." (PMID 37600714, 2023). "Based on previous research, we hypothesize that the limited IGF-1 efficacy in prostate cancer in humans is probably due to the scarcity of reliable predictive biomarkers that forecast response to IGF-1R inhibition." (PMID 36831629, 2023). "Concurrently, IGF-1R targeting in combination with other existing therapeutic options, including cytotoxic agents, radiotherapy, and castration, ought to be attempted to look for a novel strategy for the treatment of prostate cancer." (PMID 36831629, 2023). "Finally, it is worth noting that both PINCH-1 and IGF-1R are overexpressed in several other types of cancers including non-small cell lung cancer, colorectal cancer and prostate cancer 54, 58, 59, 71-74." (PMID 35401828, 2022). "Although dual inhibition of p110α+p110β can efficiently block PI3K relief of feedback inhibition and achieve potent anti-tumor effect in some prostate cancers harboring loss of PTEN, we also identified that resistance to p110α+p110β inhibition can occur through IGF1R-mediated PI3K residual activity." (PMID 34417459, 2021). "In addition, suppressing IGF1R blocks the repair of DSBs in human prostate cancer DU145 and PC3 cells and makes them sensitive to ionizing radiation." (PMID 34178997, 2021). "Employing 5-Aza treatment could trigger demethylation of AR promoter and as a consequence the expression level of IGF1R could increase significantly which may consider as a promising therapy in human prostate cancer." (PMID 33768092, 2021). "According to target prediction and pathway enrichment, the bioactive compound stadium oxygen can act on the signal pathways of prostate cancer, pathways in cancer, proteoglycans in cancer, and focal adhesion and controls the progress of liver cancer by inhibiting the overexpression of IGF1R." (PMID 32963562, 2020). "NEAT1 promoted the cell growth of prostate cancer through SRC3/IGF1R/Akt pathway." (PMID 32268876, 2020). "In addition, calorie restriction combined with IGF-1R blockade resulted in growth inhibition in prostate cancer xenografts." (PMID 32655839, 2020). "SMYD3 is also highly expressed in prostate cancer, E2F-1 could exert its IGF-1R transactivation effect through both direct and indirect pathways." (PMID 32007952, 2020). "Moreover, IGF-1R inhibition delayed the resolution of irradiation-induced DSBs in prostate cancer cells." (PMID 31467485, 2019). "Insulin-like growth factor 1 receptor (IGF1R) is a transmembrane protein, which belongs to receptor family of tyrosine kinases and is implicated in several cancers including lung, breast and prostate cancers." (PMID 31033359, 2019). "Androgen receptor could regulate the expression of IGF-1 receptor (IGF-1R) via a non-genomic pathway; for example, the re-expression of AR in M12 prostate cancer cells increased IGF-1R expression." (PMID 31126320, 2019). "Together, these data suggest that palmitoylation of Flot-1 regulates prostate cancer cell proliferation via IGF-1R signaling activation in the PM, while sumoylation of Flot-1 promotes EMT in metastatic prostate cancer via regulation of Snail stability in the nucleus." (PMID 30631151, 2019).
prostate carcinoma (continued). "Therefore, we evaluated the effect of dansylcadaverine along with the selective IGF1R tyrosine kinase inhibitors AEW541 or tyrphostin AG1024 on cell proliferation in the M12 prostate cancer cell line." (PMID 28945762, 2017). "Moreover, a phase II study with IGF1R as a molecularly targeted drug to treat prostate cancer is being conducted." (PMID 27441818, 2016). "IGF-1R has previously been shown to protect cells from DNA damaging agents, and to be critical for DNA repair by homologous recombination following radiation in prostate cancer cells." (PMID 27472395, 2016). "Notably, in prostate cancer, several clinical trials have investigated the effects of IGF-1R inhibitors in combination with other drugs, such as mitoxantrone (NCT00683475) or docetaxel." (PMID 25906745, 2015). "IGF-1R upregulation by this mechanism is able to enhance IGFs effects in prostate cancer cells." (PMID 25798130, 2015). "Additionally, a recent study suggested that growth of PC-3 prostate cancer cells in co-culture with mice calvariae was inhibited to a greater extent by a combination of IGF-1R inhibitor and simvastatin compared to either agent alone." (PMID 25895029, 2015). "Since elevated IGF-1 and IGF-1R levels have been associated with many types of cancer and metastases, they cannot be used as prostate cancer markers, at least individually, due to their lack of specificity." (PMID 24877145, 2014). "IGF-1 receptor (IGF-1R) blockade reduces prostate cancer xenograft growth." (PMID 23823800, 2013). "We hypothesized that combining calorie restriction with IGF-1R blockade would have an additive effect on prostate cancer growth." (PMID 23823800, 2013). "The expression of IGF-1R in prostate cancer remains controversial." (PMID 19171036, 2009). "It has been proposed that reduced IGF-1R action is necessary for prostate cancer progression." (PMID 19171036, 2009). "Furthermore, data from an animal model of prostate cancer progression and a prostate cancer cell line indicate an effect of IGF-1R signalling on invasion." (PMID 18598360, 2008). "This is the first study, to our knowledge, showing that the addition of exogenous IGF-1 to prostate cancer cells results in a significant increase in invasive potential, and that these effects are reduced by inhibiting IGF-1R, the MAPK pathway or the PI3-K pathway." (PMID 18598360, 2008). "However, several clinical studies showed that the development of IGF-1R mAbs (figitumumab and ganitumab) was terminated, even though they exhibited preclinical activity against IGF-1R in some tumors, such as myeloma, prostate cancer, colorectal cancer and pancreatic cancer." (PMID 36233084, 2022). "In addition, the question whether DNA methylation is involved in epigenetic regulation of the IGF1R gene was recently investigated in a series of prostate cancer cell lines representing early or advanced (metastatic) stages of the disease." (PMID 27446805, 2016). "In view of the role of fusion protein TMPRSS2-ERG in prostate cancer and to expand our previous studies on the transcriptional regulation of the IGF1R gene, we examined the hypothesis that the IGF1R gene constitutes a novel downstream target for the TMPRSS2-ERG prostate-specific chimera." (PMID 27285981, 2016). "Given the key role of fusion protein TMPRSS2-ERG in regulation of IGF1R gene expression, we decided to evaluate next the hypothesis that IGF1R targeted therapy might be more effective in prostate cancer cells expressing the fusion protein in comparison to cells that do not express the chimera." (PMID 27285981, 2016). "However, there is data that supports the idea that IGF-1 and IGF-1R could be used as biomarkers for advanced stages of prostate cancer and prostate cancer metastases." (PMID 24877145, 2014). "In addition, hypermethylation of the AR promoter may be involved in the progression of prostate cancer and downregulate expression of IGF1R." (PMID 23227263, 2012).
prostate carcinoma (continued). "Our analysis revealed that several maize miRNAs potentially target key regulators of prostate-cancer signaling, including PTEN, IGF1R, AR, FOXO1, GSK3B, and BCL2." (PMID 41440174, 2025). "To investigate how IGF-1 contributes to PD-L1 regulation, we tested effects of inhibiting signaling pathways of IGF-1R and it’s downstream effectors MEK-ERK and AKT in DU145 prostate cancer cells." (PMID 41184420, 2025). "In prostate cancer, it reduces proliferation, invasion, and migration by targeting DLX1 and IGF-1R, while sponging by oncogenic lncRNAs such as SNHG11 and MYU relieves inhibition of c-MYC, highlighting its suppressive role." (PMID 41379397, 2025). "In prostate-specific phosphatase and tensin homolog (PTEN) knockout mice (a prostate cancer model), SCFAs activate MAPK signaling via IGF1R-mediated ERK phosphorylation, thereby modulating prostate cancer growth." (PMID 41048488, 2025). "Similar to the regulation of the MAPK signaling pathway, in Pten knockout prostate cancer models, SCFAs activate PI3K signaling via IGF1R, inducing an IGF-1 autocrine loop that synergistically promotes tumor growth." (PMID 41048488, 2025). "A role of IGF–1R–mediated STAT3 activation has been reported in pancreatic and prostate cancer and melanoma." (PMID 39638246, 2024). "In vitro and in vivo experiments suggest that both IGF-1R and INSR promote angiogenesis in prostate cancer." (PMID 36755926, 2023). "IGF1R inhibition using shRNA results in autophagy induction through promoting expression levels of LC3B, leading to decreased prostate cancer progression." (PMID 35317831, 2022). "By physically interacting with IGF-1R, SDCBP activates STAT3 and thus regulates prostate cancer pathogenesis." (PMID 34445387, 2021). "Using prostate cancer cell lines DU145 and 22Rv1 we detected nuclear α- and β-subunits, with increase in nuclear signal upon IGF-treatment and reduction in response to IGF-1R inhibitor BMS-754807." (PMID 33969359, 2021). "Previous studies have shown that miR186 targeted IGF-1R in glioma, and Yin Yang 1 (YY1) and cyclin dependent kinase 6 (CDK6) in prostate cancer." (PMID 32082999, 2020). "The POU1F1-derived tumors have 499 exclusive proteins that participate in events such as Platinum drug resistance (AKT3, BCL2 and GSTT2) and Prostate cancer (FGFR1, IGF1R and PDGFD) among others." (PMID 33261069, 2020). "In the specific case of the prostate cancer-specific TMPRSS2-ERG aberrant transcription factor, we have demonstrated that the chimera was able to phosphorylate the IGF1R tyrosine kinase domain and downstream target Akt." (PMID 29455671, 2018). "In the case of human prostate cancer cell lines (PC3 and LNCaP), 24‐hrs treatment with IGF1 and insulin reduced (or tended to reduce) the expression of IGF1R, INSR and GHR, whereas only insulin increased the expression levels of Igfbp3 in LNCaP cells." (PMID 28244645, 2017). "This induction of γH2AX in MCF-7 cells is consistent with γH2AX induction by IGF-1R inhibition and IGF-1R depletion observed in prostate cancer cells." (PMID 27472395, 2016). "Cross-talk between IGF-1R and EGFR has been reported in breast, lung, and prostate cancer cells as well as in COS cells, which has stimulated interest in understanding the cooperativity between these receptors." (PMID 24904523, 2014). "Functionally, WT1 has been shown to regulate genes important in prostate cancer including VEGF, Bcl2, AR, and IGF1R." (PMID 20426842, 2010). "IGF-I binds to its receptor (IGF-1R) and activates downstream signaling pathways such as PI3K/AKT and MAPK, promoting cell proliferation and inhibiting apoptosis, thereby driving the development and progression of solid tumors such as prostate cancer." (PMID 41584612, 2025). "Also, formononetin was reported to induce the early apoptosis of prostate cancer cell DU145 via the regulation of mitochondrial apoptotic pathway and downregulation of IGF-1/IGF-1R signaling pathway." (PMID 38874510, 2024).
prostate carcinoma (continued). "IGF-1R, a receptor tyrosine kinase, promotes cancer development and metastasis by mediating ligand-independent activation of MET (receptor tyrosine kinase) in prostate cancer." (PMID 38342894, 2024). "Despite these encouraging perspectives, the multiple crosstalk between EGFR, IGF-1R and MET signaling highlighted in preclinical and clinical studies, and herein assessed in castration-tolerant prostate cancer cells, call for concomitant targeting of these three receptors." (PMID 35954439, 2022). "We used subcellular fractionation to detect both α- and β-subunits in the nucleus of both DU145 and 22Rv1 prostate cancer cells and showed by immunofluorescence microscopy that the α-subunit of nuclear IGF-1R is responsive to IGF-1R inhibition, analogous to previous results for the β-subunit." (PMID 33969359, 2021). "Several investigations also revealed that the interaction of EGFR and IGF1R may result in resistance to EGFR-TKIs in glioma and breast and prostate cancers." (PMID 30823937, 2019). "Besides, because anticarcinogenic properties of naringenin have been reported in diverse malignant tumors prostate cancer pathway consisting of eight proteins was found: AKT1, MAPK1, IGF1R, AR, CCND1, INS, PIK3CA, IGF1." (PMID 30918758, 2019). "Activating point mutations in IGF1R itself have not been reported, but there are reports of mutational inactivation or loss of heterozygosity of the anti-proliferative IGF2R in prostate cancer and uveal melanoma." (PMID 31416218, 2019). "Indeed in prostate cancers cells, suppression of RAD51, the recombinase that catalyses the strand invasion step of HR, sensitises cells to IGF-1R inhibition." (PMID 27472395, 2016). "Interestingly, IGF1R has been shown to play an important role in EMT and IGF1R activation can induce EMT in breast epithelial cells and prostate cancer cells." (PMID 26554308, 2015). "In particular, in androgen-dependent and -independent prostate carcinoma, NT157 decreases the expression of IRS proteins and downregulates IGF-1R-mediated AKT activation, leading to cell cycle arrest, apoptosis, and a delay of castrate-resistant prostate cancer progression in xenografts." (PMID 26029165, 2015). "In prostate cancer, the induced expression of INSR could increase cell proliferation, colony formation, migration, invasion and resistance to apoptosis in prostate cancer cells through the cooperation with IGF1R." (PMID 38874510, 2024). "IGF-1 induced PC3 cell proliferation, and the proliferation was increased by WT Flot-1 or KR mutant, but not CA mutant overexpression, suggesting that palmitoylation, but not sumoylation, of Flot-1 is responsible for IGF-1R signaling-mediated prostate cancer cell proliferation." (PMID 30631151, 2019). "In addition, an inverse correlation between BRCA1 and IGF1R levels was seen in androgen receptor (AR) negative prostate cancer cell lines." (PMID 28706506, 2017). "The insulin like growth factor (IGF) pathway, which includes IGF receptor-1 (IGF-1R) and its ligands, IGF-I and IGF-II, not only plays a major role in growth, development, and maintenance of homeostasis in normal cells, but also the proliferation of cancers cells, including prostate cancer cells." (PMID 23819055, 2013). "However, we have observed residual Akt phosphorylation independent of Src and IGF-1R pathways, which likely is explained by other kinases increased during prostate cancer progression, such as c-Met and Axl." (PMID 23300537, 2012). "Exosomes enriched with Src, insulin-like growth factor 1 receptor (IGF-IR), and focal adhesion kinase (FAK) proteins activate Src/FAK signaling, enhancing prostate cancer cell proliferation, migration, and angiogenesis, which may provide potential biomarkers for prostate cancer (PrCa) progression." (PMID 40002766, 2025). "Noncancerous prostate cells and prostate cancer cells respond differently to IGF exposure and IGF-1R overexpression." (PMID 39638246, 2024).
prostate carcinoma (continued). "Evidence for functional interactions between BRCA1 and androgens was suggested by experiments showing differential regulation of the IGF1R gene by BRCA1 in androgen receptor (AR) positive, as compared to AR negative, prostate cancer cells." (PMID 35432218, 2022). "In-vitro overexpression of IGF1R and INSRA, but not INSRB increased cell proliferation, colony formation, migration, invasion and resistance to apoptosis in prostate cancer cells (DU145, LNCaP, PC3)." (PMID 24809298, 2014). "Moreover new insights into the biology of the prostate and prostate cancer are provided, indicating that the IGF axis exerts different functions in malignant and non-malignant cells, a finding that might help to better understand and avoid some side effects of IGF1R targeting agents." (PMID 24809298, 2014). "In addition, there was a negative correlation between IGF1R and BRCA1 expression levels in AR-negative prostate cancer cells whereas in cells with an active AR there was a positive correlation." (PMID 35432218, 2022).